SIRT1 (sirtuin 1)
Diseases named in the same sentence as SIRT1 in open-access papers (continued):
Sharing a sentence is not in itself a finding about the gene and the disease.
cancer (continued). "SIRT1 has been shown to inhibit tumor metastasis in vitro and in vivo by impeding the EMT and reduce cell viability in H2O2-treated cancer cells by promoting the formation of reactive oxygen species, suggesting that SIRT1 plays a role as a tumor suppressor." (PMID 31317367, 2019). "SIRT1, the most characterized SIRT, is involved in many vital biological processes and plays a critical role in cancer initiation, promotion, and progression." (PMID 31726691, 2019). "We previously reported that SIRT-1, a class III lysine deacetylase, positively regulates DVL-1 proteins levels in cancer cells." (PMID 31700102, 2019). "This further suggests that SIRT1 and SIRT6 cooperate to set a threshold for FOXO3 acetylation in the cancer cells." (PMID 31357743, 2019). "Silencing information regulator 1 (SIRT1), a class III histone deacetylase, modulates the multiple biological behaviors of cancer." (PMID 31068761, 2019). "The anti-cancer effects of ISO were strongly correlated with the activation of apoptotic pathways, tubulin destabilization, SPHK1/2 inhibition, and Sirt1 activation." (PMID 31817453, 2019). "In another report, SIRT1 suppresses thesenescence in normal cells such as HDF, but it inducesthe senescence in some cancer cells such as MCF-7 andH1299 by inhibiting their growth and proliferation." (PMID 30507085, 2019). "Like SIRT1, SIRT6 is also able to reduce the transcription of MYC and HIF-1 in cancer cells by reprogramming glucose metabolism." (PMID 30761005, 2019). "Since AMPKα1, SIRT1, AKT pathways are critical pathways that are involved in the glucose metabolism and proliferation of cancer cells, we first evaluated the expression level of them in further experiment." (PMID 29374159, 2018). "These clinical data are consistent with the experimental ones reported for HCC where SIRT1 activation correlates to malignancy through MALAT1, a lncRNA highly expressed in various cancers including HCC." (PMID 30319549, 2018). "Here, we identified FR58P1a, a new mild OXPHOS uncoupler that actives the Sirt1/AMPK axis and triggers a metabolic adaptation toward glycolysis, that promotes cancer cell survival but selectively decreases the migratory capability of TNBC cells." (PMID 30181620, 2018). "Sirtuin 1 (Sirt1) is an NAD+ dependent histone deacetylase which has been shown to play a very important role in the initiation and progression of many cancers including PCa." (PMID 30651935, 2018). "A recent meta-analysis conducted on 37 selected studies of human cancers analyzed the correlations of overall survival (OS), disease-free survival (DFS) and relapse-free survival (RFS) with SIRT1 expression." (PMID 30319549, 2018). "Target genes of miR-22 so far reported include HDAC4, CDK6, SIRT1, SP1, HIF-1α and PTEN, which are involved in cancer progression." (PMID 30379969, 2018). "Analysis of RNA-seq data from 34 normal gastric tissues and 415 primary GC revealed significant upregulation of B7-H1; HDAC1–3, 6–8, and 10; and SIRT1, 3, 5, and 6 and downregulation of HDAC5 and SIRT4 in cancer (only data of B7-H1 and HDAC1–3 was presented)." (PMID 30537988, 2018). "Together, these results demonstrate a novel small-molecule activator of SIRT1 that induces autophagic cell death/mitophagy in GBM cells, which would be utilized to exploit this compound as a leading drug for future cancer therapy." (PMID 29991742, 2018). "Coupled with HDAC and SIRT1 inhibitory activity, 3'-HPT has been found to demonstrate protective effects from neurodegenerative diseases and select cancers." (PMID 28257483, 2017). "While it is undisputed that the activity of SIRT1 is correlated to the growth of several kinds of cancer cells, the exact function of SIRT2 within cancer cells was the subject of strong controversy until recently." (PMID 28989670, 2017).
cancer (continued). "Given that SIRT1 is a promising regulator of metabolism and autophagy, which are also significant for MDR in cancer cells, it is important to further explore the mechanism of USP22/SIRT1‐induced MDR in HCC cells." (PMID 28417539, 2017). "The beneficial effects of exercise, calorie restriction, and diet polyphenols (i.e., resveratrol) on cancer prevention and life-span extension also appear to be mediated by NAD+/NADH and NAD+-dependent SIRT1 activity." (PMID 28427145, 2017). "Nevertheless, our study sheds novel insight of SIRT1/LSD1/KU70 signaling and functions in cancer cells under therapeutic and environmental stress, and helps understand mechanisms of cancer drug resistance." (PMID 27384990, 2016). "miR-486 has been shown to participant in general tumorigenesis by targeting the anti-apoptotic OLFM4, SIRT1, PIM-1 and protumorigenic ARHGAP5 in various types of cancer." (PMID 27167342, 2016). "Expression of Beclin-1 and SIRT1 expression between NNM and cancer tissues was found to be statistically significant (p < 0.001)." (PMID 28070138, 2016). "Our study reveals a novel cellular stress response mechanism in cancer cells and a key role of LSD1/SIRT1/KU70 dynamic interaction in regulating DNA repair and mutation acquisition." (PMID 27384990, 2016). "SIRT1 is a multifaceted, highly conserved NAD+-dependent class III deacetylase involved in a wide variety of cellular processes including cancer." (PMID 27708228, 2016). "Furthermore, we provide evidence demonstrating that the capsaicin-induced downregulation of tNOX reduces the expression of SIRT1, which could logically explain the capsaicin-induced deteriorations in multiple cancer phenotypes, including apoptosis, cell cycle progression, and cell migration." (PMID 27367652, 2016). "It was reported that SIRT1-mediated FOXO1 deacetylation plays a key role in regulating diverse cellular processes such as differentiation and proliferation in cancer cells." (PMID 26646449, 2016). "Surprisingly, we discovered that SIRT1 and LSD1 compete for binding to KU70 in cancer cells in response to stress and have opposing roles in mediating NHEJ repair and mutation acquisition in CML and non-CML cells." (PMID 27384990, 2016). "Many studies have indicated that SIRT1 functions as a positive regulator of EMT and, more specifically, metastatic growth of cancer cells." (PMID 27528025, 2016). "SIRT1 in stromal cells promotes cancer growth by producing MMP3, whereas SIRT1 in cancer cells inhibits growth via an intracellular event." (PMID 26992208, 2016). "There are no data in the literature about the prognostic value of the combined evaluation of SIRT1 and SIRT2 protein levels in cancer patients." (PMID 25915617, 2015). "To date, SIRT1 and HDAC3 appear to be complex regulatory factors with multiple roles in cell biology and transcriptional regulation and have been suggested as anti-cancers targets." (PMID 26405459, 2015). "Collectively, these reports establish a connection between SIRT1 regulation of FOXO1, a transcription factor that in turn can influence cell growth and lipid mobilization in cancer cells." (PMID 25569080, 2015). "Altogether these results suggest that CCAR2 is required for the repair of DSBs in both normal and cancer cells and that this CCAR2 function is cell cycle and SIRT1 independent." (PMID 26158765, 2015). "Since miR-34a suppresses many oncogenes and cancer stem cell markers including CD44, CDK4, CDK6, c-Met, Notch-1, Notch-2, SIRT1 and DLL1 as its target genes, miR-34a plays important roles in cancer stem cells." (PMID 26580663, 2015).
cancer (continued). "Our results indicated that SIRT1 was involved in the crosstalk between TNF-α and β-catenin and acted as a key regulator in cancer invasion and migration." (PMID 26318035, 2015). "Moreover, strong SIRT1 expression was a significant predictor of poor survival both in univariate and multivariate analyses, further suggesting that imbalances in protein acetylation may influence cancer progression." (PMID 25569080, 2015). "Consistent with this, we assessed the mRNA expression levels of SIRT1, EFNB3, and several apoptosis-regulating genes (BIK, CASP3, CASP4, and CASP9) in MCF-7 and MDA-MB-231 cancer cells." (PMID 24489730, 2014). "Interestingly, dysregulation of apoptosis is a major hallmark of cancer cells, and it is not surprising to realize that tenovin-1 mediated SIRT1 inhibition may affect apoptosis signaling." (PMID 24743044, 2014). "SIRT1, a class III histone deacetylase, plays a critical role in regulating cancer cell growth, migration and invasion, which makes it a potential target for cancer therapeutics." (PMID 25189993, 2014). "Our results showed SIRT1 and N1IC protein expression was significantly inverse correlation in cancer tissues from 150 patients." (PMID 25420528, 2014). "This review highlights the possibility of sirtuins, especially SIRT1 and SIRT2, for cancer therapy targets, and focuses on the therapeutic potential of sirtuin modulators both in cancer prevention and treatment." (PMID 25486244, 2014). "This review presents the most significant findings of sirtuins with an emphasis on SIRT1 and SIRT2 as small-molecule modulators of SIRT1 and SIRT2 and their therapeutic potential against cancer." (PMID 25486244, 2014). "Perhaps by combining current frontline therapies, with inhibitors of SIRT1 or SIRT2, along with a FZD7 antagonist, we can create a synergistic effect in cancers with an over-active Wnt pathway." (PMID 24897117, 2014). "Overall, although numerous studies have shown that SIRT1 deacetylates HIF-1α, the functional consequences of this deacetylation on HIF1-mediated metabolic reprogramming in cancer require further elucidation." (PMID 25085992, 2014). "Sirtuin-1 (SIRT-1), a nicotinamide adenine dinucleotide (NAD+)-dependent deacetylase, has also been related to cancer development." (PMID 25533006, 2014). "Thus, SIRT1 could act as either a tumor suppressor or tumor promoter, depending on the cellular context or its targets in specific signaling pathways or specific cancers." (PMID 25486244, 2014). "Recently, the roles of SIRT1 and deleted in breast cancer 1 (DBC1) in human cancer have been extensively studied and it has been demonstrated that they are involved in many human carcinomas." (PMID 24019980, 2013). "Western blot analysis to assess SIRT1, Vimentin, E-Cadherin, LKB1, and β-actin expression was performed in gastic cancer cell lines." (PMID 23768087, 2013). "Inhibitors of SIRT1 and SIRT2 have been proposed for treatment of cancer but are far from clinical trials." (PMID 23408731, 2013). "Several target genes of miR-200a have been identified by comparing normal and cancer epithelial cells, such as ZEB1, ZEB2, SIRT1, and KEAP1." (PMID 23750238, 2013). "Consistent with this notion, sirtuins such as SIRT1 and poly-(ADP ribose) polymerase expression and activity are increased in cancer tissue." (PMID 23442768, 2013).
cancer (continued). "Associations between clinicopathological variables and the expression of SIRT1 and DBC1 in cancer tissues were investigated." (PMID 23805287, 2013). "SIRT1 activity can be regulated by the endogenous activator AROS (active regulator of SIRT1), inhibitors (deleted in breast cancer-1 (DBC1) and Tat), NAD+ concentration, and by posttranslational modifications such as phosphorylation." (PMID 23029496, 2012). "Most importantly, we discovered the new mechanisms of action of 15d-PGJ2 i.e. inhibition of SIRT1 and other histone deacetylases (HDAC) which regulate multiple mechanisms in cancer cells." (PMID 21957481, 2011). "This suggests that Sirt1 regulates WRN-mediated cellular responses to DNA damage through its deacetylation and can help to prevent cancer." (PMID 21549004, 2011). "Thesirtuin protein SIRT1 is a well studied and highly complex NAD+dependent class III histone deacetylase that has seemingly diverse functions inmetabolism, aging and cancer." (PMID 20157516, 2009). "Thus, the SIRT1–PGC-1α axis constitutes a critical senescence-evasion mechanism by preserving mitochondrial integrity and redox balance in cancer cells, particularly under TIS conditions." (PMID 41008982, 2025). "Jaridon 6 exerts its effects by inhibiting SIRT1 activity, further affecting the (Phosphatidylinositol 3-Kinase)PI3K/AKT signaling pathway, inducing autophagy, and promoting the death of drug-resistant cancer cells." (PMID 40567502, 2025). "Sirtuins, including SIRT1, SIRT3, and SIRT4, are master regulators that can exert either an activating or inhibitory effect on immune activation, depending on the cellular context and cancer type." (PMID 41425553, 2025). "SIRT1 activation has been shown to improve mitochondrial metabolism/function and to protect against age-related diseases such as CVD, neurodegenerative disorders, and cancer." (PMID 40535573, 2025). "As mentioned, SIRT1 interacts with telomeres and maintains telomere length via modulation of telomere shelterin TPP1 in mesenchymal stem cells, making berberine a promising telomere-protective drug with practical bioactivity in cancer and age-related diseases." (PMID 39858038, 2025). "Also, it is a chemosensitizer for cancer using AMPK activation, which downstream regulates SIRT1 and mTOR suppression to trigger autophagy." (PMID 39858038, 2025). "Furthermore, miR-30e-5p reduces tumorigenesis by targeting Sirt1/JAK/STAT3 signaling, which plays a critical role in cancer cell survival, proliferation and immune evasion." (PMID 40805201, 2025). "ASCs with TRAF3IP2 knockdown (ASCTRAF3IP2KD) did not exhibit changes in TRAF3IP2, NAMPT or SIRT1 levels, indicating a cancer-specific effect of TRAF3IP2 silencing." (PMID 41436543, 2025). "Although SIRT1 and SIRT3 are generally protective of normal tissue, inhibiting them in cancer cells could potentially enhance the effectiveness of chemotherapy." (PMID 41425553, 2025). "SIRT1 is the most studied NAD-dependent histone deacetylase, and the SIRT1 signaling pathway is closely related to many important pathways that regulate senescence, and also plays an important role in cancer development." (PMID 40292294, 2025). "Two sirtuins of interest for targeted cancer therapy include SIRT1 and SIRT2, which deacetylate histones H3, H4, and nonhistone substrates, playing a key role in DNA repair and oxidative stress mitigation." (PMID 41333420, 2025).
cancer (continued). "Taken together, there is compelling evidence to suggest that targeted inhibition of SIRT1 and SIRT2 may inhibit DNA repair and reduce the ability of cancer cells to resist oxidative stress induced by radiation." (PMID 41333420, 2025). "Resveratrol deacetylates SIRT1 and activates hepatic Liver Kinase B1 (LKB1), leading to an increase in AMPK activity, which stimulates energy catabolism and improves cellular NAD+ levels, resulting in cancer inhibition." (PMID 39479446, 2024). "Interestingly, SIRT1 and FOXO3 have been shown to play critical roles in various types of cancer, typically influencing tumor progression by regulating cell growth, apoptosis, and autophagy." (PMID 39266959, 2024). "Indeed, the use of NAM as an inhibitor of both Sirt1 and poly-ADP-ribose polymerases has been proposed for cancer chemoprevention and therapy, especially in those malignancies where NNMT has been reported to be upregulated." (PMID 39273039, 2024). "HULC lncRNA has been reported to correlate with Sirt1 protein levels in human HCC tissues positively and can be used in RCCfor stabilizing Sirt1 protein and triggering autophagy to attenuate the chemosensitivity of HCC and other cancer cells." (PMID 39682093, 2024). "Thus, SIRT1 is integral in regulating AMPK and downstream targets, influencing autophagy in human cancers." (PMID 39403142, 2024). "Sinapic acid is a potent anti-oxidant used for the treatment of cancer, infections, oxidative stress, and inflammation; its anti-cancer mechanism works through the regulation of multiple proteins (CTNNB1, PRKCA, CASP8, SIRT1) and cytochrome enzymes (CYP1A1, CYP3A4)." (PMID 38999065, 2024). "In addition, we also found that the expression level of SIRT1 was significantly correlated with the PFI of patients with KIRC, LGG, and GBM and that it had a protective effect on all three cancers." (PMID 39845948, 2024). "Here, we highlight that, downstream of VDR, small molecule activators for SIRT1 such as SRT1720 offer an alternative approach and a therapeutic hope for these cancers if they could be directed specifically to cancer cells." (PMID 39494323, 2024). "In addition, TBXT mediates tamoxifen resistance by silencing the expression of sirtuin-1 (SIRT1), an oncogene that has been observed to be overexpressed in a variety of cancers." (PMID 38965548, 2024). "While the role of SIRT1 in specific cancer types has been extensively researched, there is a lack of comprehensive studies on its involvement in pan-cancers." (PMID 39845948, 2024). "Interestingly, the anti-cancer effect of Sirt6 seems more apparent in interaction with Sirt1, inducing MDM2-dependent Sirt1 degradation or potentiating the DNA damage response." (PMID 38254877, 2024). "Interestingly, due to the different subcellular localization of SIRTs, SIRT1 and SIRT2 are localized in the nucleus and cytoplasm of the cell, and play diverse functions in cancer." (PMID 39479446, 2024). "Given that the contributions of ISG15 and SIRT1 to cancer pathogenesis are complex and remain elusive, we analyzed the mRNA and protein expression levels of ISG15 and SIRT1 in The Cancer Genome Atlas (TCGA) and the Cancer Cell Line Encyclopedia (CCLE) database." (PMID 38443596, 2024). "Consequently, SIRT7 propels the activation of SIRT1, initiating SIRT1-mediated deacetylation and activation of the AKT/p70S6K1 signaling cascade that in turn stimulates the growth and survival of cancer cells." (PMID 38383727, 2024). "These analyses suggested that, although SIRT1 inhibition increased the frequency of initiation concomitant with the enhanced prevalence of R-loops in cancer cells, age progression did not trigger additional replication initiation events in adult fibroblasts." (PMID 37998365, 2023).